ERCC3 (ERCC excision repair 3, TFIIH core complex helicase subunit)
Description:
ATP-dependent 3'-5' DNA helicase/translocase. Binds dsDNA rather than ssDNA, unzipping it in a translocase rather than classical helicase activity. Component of the general transcription and DNA repair factor IIH (TFIIH) core complex. When complexed to CDK-activating kinase (CAK), involved in RNA transcription by RNA polymerase II. The ATPase activity of XPB/ERCC3, but not its helicase activity, is required for DNA opening; it may wrap around the damaged DNA wedging it open, causing localized melting that allows XPD/ERCC2 helicase to anchor. In transcription, TFIIH has an essential role in transcription initiation. When the pre-initiation complex (PIC) has been established, TFIIH is required for promoter opening and promoter escape. The ATP-dependent helicase activity of XPB/ERCC3 is required for promoter opening and promoter escape. In transcription pre-initiation complexes induces and propagates a DNA twist to open DNA. Also involved in transcription-coupled nucleotide excision repair (NER) of damaged DNA. In NER, TFIIH acts by opening DNA around the lesion to allow the excision of the damaged oligonucleotide and its replacement by a new DNA fragment. The structure of the TFIIH transcription complex differs from the NER-TFIIH complex; large movements by XPD/ERCC2 and XPB/ERCC3 are stabilized by XPA. XPA retains XPB/ERCC3 at the 5' end of a DNA bubble (mimicking DNA damage).
Synonyms: XPB; BTF2; RAD25; Ssl2; GTF2H; TFIIH; TTD2
Tractability: Small molecule: a structure with a bound ligand is known. PROTAC: ubiquitination databases record sites on it; its protein half-life has been measured.
Target class: Enzyme; Hydrolase
Gene: Protein-coding gene on chromosome 2 (127,257,285 to 127,294,188, reverse strand). Ensembl gene ENSG00000163161.
Subcellular location: Nucleus
Subcellular location (Human Protein Atlas): Nucleoplasm; Vesicles
Pathways (Reactome):
Gene expression (Transcription): Formation of RNA Pol II elongation complex; Formation of the Early Elongation Complex; NoRC negatively regulates rRNA expression; RNA Pol II CTD phosphorylation and interaction with CE; RNA Polymerase I Promoter Escape; RNA Polymerase I Transcription Initiation; RNA Polymerase I Transcription Termination; RNA Polymerase II Pre-transcription Events; RNA Polymerase II Promoter Escape; RNA Polymerase II Transcription Elongation; RNA Polymerase II Transcription Initiation; RNA Polymerase II Transcription Initiation And Promoter Clearance; RNA Polymerase II Transcription Pre-Initiation And Promoter Opening
Disease: Formation of HIV elongation complex in the absence of HIV Tat; Formation of HIV-1 elongation complex containing HIV-1 Tat; Formation of the HIV-1 Early Elongation Complex; HIV Transcription Initiation; RNA Pol II CTD phosphorylation and interaction with CE during HIV infection; RNA Polymerase II HIV Promoter Escape; Tat-mediated elongation of the HIV-1 transcript; Transcription of the HIV genome
DNA Repair: Dual Incision in GG-NER; Dual incision in TC-NER; Formation of Incision Complex in GG-NER; Formation of TC-NER Pre-Incision Complex; Gap-filling DNA repair synthesis and ligation in TC-NER; Transcription-Coupled Nucleotide Excision Repair (TC-NER)
Metabolism of RNA: mRNA Capping
Gene Ontology:
Molecular function: 3'-5' DNA helicase activity; ATP hydrolysis activity; protein binding; damaged DNA binding; DNA binding; ATP binding; DNA helicase activity; hydrolase activity; promoter-specific chromatin binding
Biological process: apoptotic process; DNA repair; DNA topological change; hair cell differentiation; intracellular protein localization; nucleotide-excision repair; positive regulation of apoptotic process; regulation of mitotic cell cycle phase transition; response to oxidative stress; response to UV; transcription by RNA polymerase II; transcription initiation at RNA polymerase II promoter; transcription-coupled nucleotide-excision repair; embryonic organ development; transcription elongation by RNA polymerase II
Cellular component: nucleoplasm; transcription factor TFIID complex; transcription factor TFIIH core complex; transcription factor TFIIH holo complex; nucleotide-excision repair factor 3 complex; nucleus; transcription preinitiation complex
Genetic constraint (gnomAD): Loss-of-function variants: 53 observed, 83.63 expected, observed/expected ratio (o/e) 0.63, 90% interval 0.51 to 0.8. The upper end of that interval is the gene's LOEUF score, 0.8, which puts it in group 3 of 6, group 1 being the genes least tolerant of losing a copy. Missense variants: 766 observed, 940.59 expected, observed/expected ratio (o/e) 0.81, 90% interval 0.77 to 0.86. Synonymous variants: 327 observed, 357.8 expected, observed/expected ratio (o/e) 0.91, 90% interval 0.83 to 1.
Gene-disease validity (ClinGen):
ClinGen rates the evidence that ERCC3 causes each of these diseases.
xeroderma pigmentosum group B (autosomal recessive): Definitive.
Cancer hallmarks: escaping programmed cell death (suppresses); genome instability and mutations (suppresses)
Homologues: Orthologues: chimpanzee ERCC3 (99% identical), macaque ERCC3 (99% identical), rabbit ERCC3 (98% identical), pig ERCC3 (98% identical), dog ERCC3 (97% identical), guinea pig ERCC3 (97% identical), mouse Ercc3 (96% identical), rat Ercc3 (95% identical), zebrafish ercc3 (89% identical), tropical clawed frog ercc3 (74% identical), Drosophila melanogaster hay (70% identical), Caenorhabditis elegans xpb-1 (65% identical).
Diseases named in the same sentence as ERCC3 in open-access papers:
ERCC3 is named in the same sentence as 61 diseases in open-access papers, as found by Europe PMC text mining. Sharing a sentence is not in itself a finding about the gene and the disease. The quoted sentences say what the papers report.
xeroderma pigmentosum (34 papers, 2008 to 2025). Xeroderma pigmentosum (XP) is a rare genodermatosis characterized by extreme sensitivity to ultraviolet (UV)-induced changes in the skin and eyes, and multiple skin cancers. "Intriguingly, mutations in ERCC3, a known cancer gene, can result in xeroderma pigmentosum with Cockayne syndrome or trichothiodystrophy, which are prominent diseases associated with defective DNA repair and predisposition to skin cancer." (PMID 29221109, 2017). "In humans, mutations in ERCC3 result in skin disorders, such as xeroderma pigmentosum, cockayne syndrome and trichothiodystrophy, which result in sensitivity to UV radiation and oxidative stress." (PMID 29247174, 2017). "ERCC3 mutation is associated with xeroderma pigmentosum and breast cancer." (PMID 28813025, 2017). "Moreover, the xeroderma pigmentosum, complementation group B (XPB/ERCC3) gene encodes an ATP-dependent DNA helicase that functions in TCR/NER; the encoded protein is a subunit of basal transcription factor 2 (TFIIH) and, therefore, also functions in class II transcription." (PMID 35052761, 2021). "Rare germline variants in ERCC3, XPA, and XPC are related to xeroderma pigmentosum, a disease that increases the appearance of ultraviolet-induced skin cancer at an early age." (PMID 39408606, 2024). "g.,ERCC2/XPD,ERCC3/XPB,ERCC4/XPF,ERCC5/XPG,ERCC6/CSB, andERCC8) in the NER pathway frequently cause Xeroderma pigmentosum, trichothiodystrophy, or Cockayne syndrome." (PMID 35593466, 2022). "Mutations in a second gene encoding a putative DNA helicase (originally designated ERCC3 and subsequently named XPB) were linked to Xeroderma pigmentosum and Cockayne syndrome in 1990." (PMID 32120966, 2020). "These diseases include xeroderma pigmentosum (XP) which is due to a defect in one of approximately eleven XP associated genes (including XPA, ERCC3 (XPB), XPC, and POLH (XPV))." (PMID 23285288, 2012). "In humans, the defects in XPD/ERCC2 and XPB/ERCC3 genes lead to xeroderma pigmentosum (XP) and Cockayne's Syndrome (CS)." (PMID 21375739, 2011). "The clinical function of ERCC3 is clearly known to be associated with inherited disease including UV-hypersensitive NER syndromes xeroderma pigmentosum (XP), Cockayne Syndrome (CS), combined XP and CS (XP/CS), and trichothiodystrophy (TTD)." (PMID 30417012, 2018). "Biallelic pathogenic variants in one of the seven NER genes coding for the so-called complementation groups, XPA, ERCC3, XPC, ERCC2, DDB2, ERCC4, ERCC5, the NER gene ERCC1, and the gene coding for XP variant, POLH, are the causes of the rare hereditary disease Xeroderma pigmentosum (XP)." (PMID 35174087, 2022).
Cockayne syndrome (15 papers, 2008 to 2026). A multisystem condition characterized by short stature, a characteristic facial appearance, premature aging, photosensitivity, progressive neurological dysfunction, and intellectual deficit. "Among these disorders are Cockayne syndrome which is caused by mutations in ERCC6 (CSB) or ERCC8 (CSA), trichothiodystrophy (TTD) caused by mutations in ERCC2 (XPD), ERCC3 (XPB), or TTDA (GTF2H5) and XPF-ERCC1 progeria (XFE) caused by dysfunction of the XPF-ERCC1 heterodimer." (PMID 23947592, 2013).
trichothiodystrophy (15 papers, 2008 to 2025). Trichothiodystrophy or TTD is a heterogeneous group disorders characterized by short, brittle hair with low-sulphur content (due to an abnormal synthesis of the sulfur containing keratins). "Trichothiodystrophy with ERCC2 and ERCC3 mutations is caused by defective DNA repair after UV damage, and hypomyelination was reported in trichothiodystrophy with ERCC2 mutation." (PMID 29451896, 2018). "In the Fe–S helicases XPB (ERCC3) and XPD (ERCC2), recurrent missense mutations fall within the helicase core or the TFIIH-interacting interfaces, explaining the spectrum of transcription and repair defects underlying Xeroderma Pigmentosum (XP) and Trichothiodystrophy (TTD)." (PMID 41302153, 2025).
breast carcinoma (9 papers, 2017 to 2026). "Three patients carried pathogenic variants in hereditary cancer genes unrelated to their phenotype, and a heterozygous ERCC3 pathogenic variant was detected in a young patient with breast cancer." (PMID 41990296, 2026). "The excision repair cross-complementation group 3 gene (ERCC3) has recently been identified as a breast cancer susceptibility gene in various cohorts of different geographical and ethnic origin." (PMID 39742368, 2024). "In recent years, the excision repair cross-complementation group 3 gene (ERCC3) was proposed as a susceptibility gene for breast cancer." (PMID 39742368, 2024). "Bioinformatic analysis revealed that ERCC3 expression was negatively associated with estrogen receptor (ER), progesterone receptor (PR), nontriple-negative status, and nodal status of breast cancers." (PMID 39742368, 2024). "ERCC3 truncating mutation has the potential to serve as a biomarker for the pathological diagnosis of breast cancers." (PMID 39742368, 2024). "Up to now, only 13 ERCC3 truncating and splicing mutations have been reported in a minimum of 29 breast cancer patients and confer a 1.53 ∼ 3.54-fold breast cancer risk." (PMID 39742368, 2024). "In the same context, ERCC3 germline mutations were previously identified in families with multiple breast cancer cases." (PMID 38313678, 2024). "The polymorphisms of ERCC3 have been reported to be associated with several cancers, such as colorectal cancer, pancreatic cancer, breast cancer, and OS." (PMID 35860595, 2022). "ERCC3 copy number variant (CNV) detection may help confirm histopathological type of breast cancer and breast cancer metastasis." (PMID 39742368, 2024). "The c.348C > G (p.Y116X) mutation may be involved in breast cancer by causing reduction in ERCC3 expression." (PMID 39742368, 2024). "Since the absence of common variant with a high allele frequency in our study, more genetic analysis studies in larger cohorts from different regions as well as functional studies are warranted to estimate the relative risk for breast cancer conferred by ERCC3 mutations." (PMID 39742368, 2024). "In conclusion, this study revealed that ERCC3-truncating mutation p.Y166X may contribute to the breast cancer development in Han-Chinese population." (PMID 39742368, 2024). "The ERCC3 mutation p.Y116X may increase breast cancer risk in the Han-Chinese population." (PMID 39742368, 2024). "In this case-control study among a Han Chinese population composed of 592 participators, we assessed the role of ERCC3 variants including a novel germline nonsense variant c.348C > G (p.Y116X) and two missense variants rs754010782 (p.R360C) and rs371627165 (p.V471I) in breast cancer pathogenesis." (PMID 39742368, 2024). "For example, previous researches have displayed significant correlations between single nucleotide polymorphisms in ERCC2, ERCC3, and ERCC4 and the risk of developing lung, skin, and breast cancers." (PMID 39192988, 2024). "The nontriple-negative breast cancer group also displayed a lower level of ERCC3 expression than the triple-negative breast cancer group." (PMID 39742368, 2024). "By exploring ERCC3 gene genomic alterations in breast cancers using c-BioPortal, we found that ERCC3 amplification concentratedly occurred in breast invasive cancer NOS, and most of deep deletions occurred in metaplastic breast cancer." (PMID 39742368, 2024). "A total of 7101 breast cancer patients from 8 studies were involved in analysis by c-BioPortal, and 1.2% had ERCC3 gene genomic alterations." (PMID 39742368, 2024). "Our findings also imply that ERCC3-truncating mutation and CNV have potential clinical significance in pathological diagnosis of breast cancer." (PMID 39742368, 2024). "Polymorphisms ERCC3/XPB, NEIL-2, NTH-1, and FEN-1 have been studied in lung, gastric, lung, and breast cancer." (PMID 38892180, 2024).
breast carcinoma (continued). "Considering ERCC3 gene, a missense variation Ser704Leu was identified in a breast cancer patient with multiple affected relatives." (PMID 38313678, 2024). "ERCC3 exhibits potential as a biomarker for the pathological diagnosis of breast cancer." (PMID 39742368, 2024). "A novel ERCC3 mutation p.Y116X was identified in a breast cancer family, while no frequency bias for the genotype and allele of rs754010782 and rs371627165 was observed (all P > 0.05)." (PMID 39742368, 2024). "Other genes with moderate, low, or uncertain penetrance that have been implicated in breast cancer, RECQL, RAD51B, ERCC3, MRE11A, RAD51D, BARD1, and NBN, had a yield of 0.3% (n = 7), 0.3% (n = 7), 0.3% (n = 6), 0.3% (n = 6), 0.2% (n = 4), 0.2% (n = 4), and 0.1% (n = 3), respectively." (PMID 35971132, 2022). "Impaired ERCC3 function in NER may be a potential pathogenesis for breast cancer." (PMID 39742368, 2024). "Amplification of ERCC3 primarily occurred in breast invasive cancer not otherwise specified (NOS), while most of deep deletions occurred in metaplastic breast cancer." (PMID 39742368, 2024).
skin cancer (7 papers, 2009 to 2024). "Five of the variants were singletons, and one was a doubleton: rs34295337 in ERCC3, a gene associated with xeroderma pigmentosum type B, which is a rare autosomal recessive disease that is associated with skin cancer." (PMID 28502252, 2017). "Accordingly, all five specific skin cancer genes from the NER class - DDB2, ERCC3, ERCC5, XPA, and XPC - are associated with UV-sensitive skin." (PMID 26856619, 2016). "Patients with ERCC3 mutations manifest NER-defective syndromes including xeroderma pigmentosum group B (OMIM 610651) and trichothiodystrophy 2 (OMIM 616390) and have a high increased risk for skin cancer." (PMID 39742368, 2024).
gastric cancer (4 papers, 2021 to 2025). A primary or metastatic malignant neoplasm involving the stomach. "For instance, ERCC5 rs1047768 variant reduced the risk of gastric cancer, ERCC3 rs4150403 was associated with an increased susceptibility to head and neck cancer in Caucasians, and ERCC6 rs4253132 polymorphism decreased the risk of head and neck cancer among African Americans." (PMID 33557438, 2021). "Consistently, vital studies have indicated that miR-192-5p plays a role in the resistance of EC and gastric cancer to chemotherapy, which reverses cisplatin resistance by targeting ERCC3 and ERCC4 in gastric cancer lines." (PMID 33708127, 2021). "Upregulation of miR187 in gastric cancer significantly downregulated the protein expression of Smad4, TGF-β1, and NER components (ERCC3 and ERCC4), which boosted the cisplatin sensitivity." (PMID 40303493, 2025).
ovarian carcinoma (4 papers, 2021 to 2025). A malignant neoplasm originating from the surface ovarian epithelium. "This strongly argues against a role for ERCC3 in ovarian cancer predisposition." (PMID 39794353, 2025).